ECHDC3 (enoyl-CoA hydratase domain containing 3)
Description:
May play a role in fatty acid biosynthesis and insulin sensitivity.
Synonyms: FLJ20909
Tractability: Small molecule: it has a high-quality binding pocket. PROTAC: its protein half-life has been measured.
Gene: Protein-coding gene on chromosome 10 (11,742,366 to 11,764,139, forward strand). Ensembl gene ENSG00000134463.
Subcellular location: Mitochondrion
Gene Ontology:
Molecular function: enoyl-CoA hydratase activity; hydro-lyase activity
Biological process: positive regulation of cellular response to insulin stimulus; fatty acid metabolic process
Cellular component: mitochondrion
Genetic constraint (gnomAD): Loss-of-function variants: 15 observed, 14.18 expected, observed/expected ratio (o/e) 1.06, 90% interval 0.71 to 1.61. The upper end of that interval is the gene's LOEUF score, 1.61, which puts it in group 6 of 6, group 1 being the genes least tolerant of losing a copy. Missense variants: 266 observed, 239.57 expected, observed/expected ratio (o/e) 1.11, 90% interval 1 to 1.23. Synonymous variants: 114 observed, 95.51 expected, observed/expected ratio (o/e) 1.19, 90% interval 1.02 to 1.39.
Homologues: Orthologues: chimpanzee ECHDC3 (99% identical), macaque ECHDC3 (96% identical), rabbit ECHDC3 (83% identical), mouse Echdc3 (82% identical), guinea pig ECHDC3 (81% identical), rat Echdc3 (81% identical), dog ECHDC3 (78% identical), pig ECHDC3 (63% identical), Caenorhabditis elegans ech-2 (41% identical), Drosophila melanogaster CG6984 (40% identical). Paralogues in human: ECHS1 (29% identical), ECHDC2 (25% identical), AUH (25% identical), CDYL (25% identical), CDYL2 (25% identical), CDY1B (22% identical), CDY2A (22% identical), CDY2B (22% identical), CDY1 (21% identical), ECH1 (20% identical), HIBCH (19% identical), ECI1 (19% identical), and 1 more.
Diseases named in the same sentence as ECHDC3 in open-access papers:
ECHDC3 is named in the same sentence as 18 diseases in open-access papers, as found by Europe PMC text mining. Sharing a sentence is not in itself a finding about the gene and the disease. The quoted sentences say what the papers report.
acute coronary syndrome (2 papers, 2014 to 2016). Signs and symptoms related to acute ischemia of the myocardium secondary to coronary artery disease. "We previously reported a correlation between ECHDC3 upregulation and the severity of acute coronary syndrome." (PMID 27586541, 2016). "ECHDC3 over-expression was reported in onset of acute coronary syndrome." (PMID 24612859, 2014). "In a microarray-based gene expression study performed previously by our research team, we found that ECHDC3 mRNA expression was significantly increased within 2 h after an acute coronary syndrome, suggesting this gene could be a potential novel biomarker for the early stage of an acute episode." (PMID 27586541, 2016).
leukemia (2 papers, 2022 to 2023). A malignant (clonal) hematologic disorder, involving hematopoietic stem cells and characterized by the presence of primitive or atypical myeloid or lymphoid cells in the bone marrow and the blood. "Knocking down ECHDC3 in AML cells by RNAi promoted the death of leukemia cells with cytarabine and doxorubicin." (PMID 36172164, 2022). "RELL2 expression appeared to be correlated with ECHDC3 in this study, and data suggest that ECHDC3 may increase the chemoresistance of leukemia." (PMID 37893069, 2023). "The mt-DNA transcriptomes (MT-CO1, MT-CO2, ND1, ND2, and ND3) did not alter by inhibiting ECHDC3, whereas knocking down of ECHDC3 promoted the death of leukemia cells in either Ara-C at 0.1–1 μM or DOX at 0.04–0.16 μg/ml." (PMID 36172164, 2022).
acute myeloid leukemia (1 paper, 2022). Acute myeloid leukemia (AML) is a group of neoplasms arising from precursor cells committed to the myeloid cell-line differentiation. "Enoyl-CoA hydratase domain containing 3 (ECHDC3) increased in CD34+ progenitor cells of acute myeloid leukemia (AML) cells after chemotherapy." (PMID 36172164, 2022).
colorectal cancer (1 paper, 2022). A primary or metastatic malignant neoplasm that affects the colon or rectum. "ECHDC3 has a role in fatty acid biosynthesis and has been found to have an increased expression in the brains of Alzheimer's patients while USP6NL is a GTPase-activating protein for Rabs and is up-regulated in several cancers, including breast and colorectal cancers." (PMID 35782544, 2022).
myocardial ischemia (1 paper, 2016). A disorder of cardiac function caused by insufficient blood flow to the muscle tissue of the heart. "The ECHDC3 role in CVD is scarcely explored to allow a more comparative discussion of our data, but is known that ECHDC2 upregulation in cardiac tissue of rats was related to increased susceptibility to myocardial ischemia/reperfusion injury." (PMID 27586541, 2016).
Sepsis (1 paper, 2025). Sepsis is defined as life-threatening organ dysfunction caused by a dysregulated host response to infection. "ECHDC3 exhibited markedly higher expression in sepsis patients in our study, which destroyed the fatty acid biosynthesis and lipid metabolism." (PMID 40421007, 2025). "Among them, YME1L1, THEM4, and COQ10A showed significantly lower expression levels in sepsis samples, while ECHDC3 exhibited markedly higher expression." (PMID 40421007, 2025). "We think that both YME1L1 and ECHDC3 may be the potential role in the mechanism of sepsis which may provide new insights into the pathophysiology of the disease." (PMID 40421007, 2025). "Subsequent gene expression analysis revealed that YME1L1, THEM4, and COQ10A exhibited significantly lower expression levels in sepsis patient samples from both the GSE95233 and GSE28750 datasets, while ECHDC3 demonstrated markedly higher expression in sepsis patients (p < 0.05)." (PMID 40421007, 2025). "Consequently, YME1L1, THEM4, COQ10A, and ECHDC3 were identified as biomarkers for sepsis." (PMID 40421007, 2025). "This may verify that ECHDC3 can prompt the development of sepsis by regulating lipid metabolism." (PMID 40421007, 2025). "Four biomarkers (YME1L1, ECHDC3, THEM4, and COQ10A) related to mitochondrial and macrophage polarization in sepsis were obtained by differential expression, machine learning, and expression validation." (PMID 40421007, 2025). "Therefore, machine learning and gene expression analysis were utilized in this study to identify YME1L1, ECHDC3, THEM4, and COQ10A as biomarkers for sepsis in our study." (PMID 40421007, 2025).
systemic lupus erythematosus (1 paper, 2021). An autoimmune multi-organ disease typically associated with vasculopathy and autoantibody production. "The remaining variants rs56402156, rs7920721, and rs4351014 (in/near EPHA1, ECHDC3, and HS3ST1) have not been directly associated with other traits, although their associated genes were implicated in systemic lupus erythematosus (HS3ST1) and cancer (EPHA1, ECHDC3)." (PMID 34992629, 2021).
unstable angina (1 paper, 2016). "It was previously reported that ECHDC3 mRNA expression was significantly increased in patients with ST-segment elevation myocardial infarction when compared to unstable angina, indicating its association with the severity of CVD." (PMID 27586541, 2016).
cancer (4 papers, 2021 to 2023). A tumor composed of atypical neoplastic, often pleomorphic cells that invade other tissues. "The remaining genes in the hyperloss category are ECHDC3, KRTCAP3, LURAP1, and MAMDC4, none of which are known drivers in cancer." (PMID 37245006, 2023).
tumor (2 papers, 2022). "Higher mRNA levels of ACAP2, ECHDC3, EGR1, and CD74 were highly associated with tumor development." (PMID 35999505, 2022).
cardiovascular diseases (1 paper, 2016). "Increased levels of monounsaturated fatty acids, especially oleic acid, and ECHDC3 upregulation in patients with coronary artery lesion suggests that these are independent factors associated with the initial progression of cardiovascular disease." (PMID 27586541, 2016). "However, the function of ECHDC3 or its involvement with cardiovascular diseases is scarcely explored in the literature, which might be due to its recent identification." (PMID 27586541, 2016). "ECHDC3 shares 30 % identity with ECHDC2, and these proteins may possibly have similar functions in the pathophysiology of cardiovascular diseases." (PMID 27586541, 2016).
metabolic disease (1 paper, 2021). A congenital disorder (due to inherited enzyme abnormality) or acquired (due to failure of a metabolically important organ) disorder resulting from an abnormal metabolic process. "ECHDC3 is one of the candidate genes for PW, and ECHDC3 is a kind of testis-tissue sperm-binding protein-encoded gene, and studies have shown that it was mainly related to metabolic disease and insulin sensitivity, and might affect the growth of animals." (PMID 34203505, 2021).
ECHDC3 also shares sentences with these, for which no sentence is quoted: Alzheimer disease (1 paper); anaphylaxis (1); autism (1); dyslipidemia (1); gastroenteropathy (1); Intellectual disability (1).